IL1B (interleukin 1 beta)
Diseases named in the same sentence as IL1B in open-access papers (continued):
Sharing a sentence is not in itself a finding about the gene and the disease.
bacterial infection (continued). "TNF-α is a type II homotrimeric membrane protein that plays a key regulatory role in inflammation and host defense against bacterial infection, and IL-1β is a multifunctional cytokine involved in many immune and pro-inflammatory responses." (PMID 37251563, 2023). "Another study found that MEG3 regulates the immune response to bacterial infection in lungs through binding to miR-138 competitively with IL-1β, increasing IL-1β concentration." (PMID 36869839, 2023). "Previous studies have shown that Cxcl1/Cxcl2/Il1b axis in neutrophils plays a major role in inflammatory response during bacterial infections." (PMID 38149246, 2023). "While IL-1β is mainly induced in macrophages during inflammation, its induction in neutrophils has also been demonstrated in several examples of bacterial infection." (PMID 37910490, 2023). "We found that IL-18 negatively regulated the severity of the skin inflammation induced by the bacterial infection, whereas IL-1β was involved in controlling the bacterial burden." (PMID 37910490, 2023). "IL-1β is a pleiotropic cytokine, which is a key mediator of inflammatory response and plays a crucial role in the host’s defense against bacterial infection." (PMID 36541752, 2023). "The cytokines TNF-α, IL-6, IL-12/IL-23 p40, and IL-1β were measured in this experimental set-up as they are highly important for the defense against a bacterial infection: the release of TNF-α increases phagocytic capacities of macrophages." (PMID 37654489, 2023). "NLRP3 inflammasome activation is a highly regulated process for controlling the secretion of potent inflammatory cytokines, such as IL-1β and IL-18, which are essential during bacterial infection and the inflammatory response." (PMID 38001788, 2023). "The secretion of IL-1β and IL-18 in human macrophages treated with β-hemolysin from S. agalactiae was associated with NLRP3 inflammasome activation during bacterial infection-mediated fetal death." (PMID 36761775, 2023). "The presence of GIV in murine macrophages was reported to inhibit the expression of proinflammatory cytokines IL-6 and IL-1β during bacterial infection." (PMID 38005948, 2023). "IL-1β has been shown to be protective in several bacterial infection models by promoting rapid recruitment of neutrophils to inflammatory sites, induction of cytokines and chemokines and stimulation of Th17 responses." (PMID 37111466, 2023). "Specifically related to oral health, in vitro herbal extracts can indeed modulate gingival cytokine expression in response to bacterial infection and reduce the host pro-inflammatory signals in gingival epithelial cells such as IL-8 and IL-1β." (PMID 37237883, 2023). "The levels of interleukin (IL)-1β, IL-6 and IL-8 were quantified through a molecular assay, indicating that the peptide was able also to regulate the inflammatory response following bacterial infection." (PMID 37111266, 2023). "It is well and long ago established that IL-1β and C3 play critical roles in the first line defense against bacterial infection." (PMID 36026499, 2022). "Similar to our results, the expression of IL-1β significantly increased at 12 h and then decreased between 12 and 24 h following a bacterial infection in Piaractus mesopotamicus." (PMID 35309129, 2022). "NFκB mediates responses to viral and bacterial infections by releasing cytokines, including IL-1β, IL-6, and TNF-α." (PMID 36362264, 2022). "In particular, we identified that FFAR2+TNFAIP6+ NEUs and THBS1+IL1B+ MOs undertook an important role in the immune response to bacterial infection." (PMID 36119025, 2022). "Studies have shown that IAV inhibits bacterial-induced interleukin-1β (IL-1β) production and impairs host defense against bacterial infection." (PMID 36389138, 2022). "AIM2 was identified as the receptor involved in inflammasome activation in response to the recognition of cytosolic DNA during bacterial infections leading to the production of IL-1β and IL-18, and pyroptosis." (PMID 36033879, 2022).
bacterial infection (continued). "As well-known inflammatory cytokines or chemokines, TNF-α, IL-1β, IL-6, and IL-8 are involved in various types of inflammatory responses and are crucial in inflammatory processes during bacterial infection in bovine mammary glands." (PMID 35681915, 2022). "In the present study, the observed increase in il-1β expression from infected gilthead seabream was in line with that already observed in teleosts submitted to bacterial diseases." (PMID 35163486, 2022). "Pro-inflammatory cytokines associated with viral or bacterial infections such as tumor necrosis factor-alpha (TNFα), interleukin-6 (IL6), or interleukin-1beta (IL1β) are known to affect many liver functions or synthetic activities." (PMID 36499207, 2022). "Similar to our findings, the levels of pro-inflammatory cytokines, IL-6, TNF-α, and IL-1β, tested after bacteriophage administration, were significantly lower than in the group with developed bacterial infection, treated with PBS alone." (PMID 36211337, 2022). "Blockade of IL-1β can increase viral and bacterial infections, indicating an important function of this central cytokine in combatting common infectious pathogens." (PMID 33924019, 2021). "Here, dietary glutamine supplementation significantly decreased the expression of il-8 in the gill at 1 d, and the expression of il-1β at 30 d, which contributed to the decreased mortality after bacterial infection." (PMID 35052548, 2021). "This is consistent with the results of a previous study, which showed that IL-1β is required for the pathogenicity of Th17 during intracellular bacterial infection." (PMID 34276692, 2021). "Dietary glutamine supplementation promoted quicker inflammatory responses in the head-kidney and spleen at 1 d to fight against bacterial infection, indicated by the increased expression of il-8 and il-1β." (PMID 35052548, 2021). "Then, using mouse models, we demonstrated that TRM17 cells persist in the tissue after bacterial infection and can rapidly respond to inflammatory stimuli, such as IL-1β by producing IL-17A, which ultimately aggravates immune-mediated tissue injury." (PMID 33622974, 2021). "Increased expression in the Nlrp3 (Cryopyrin) gene suggests that the MCs can have a stronger ability to release pro-inflammatory cytokines such as IL-1β and IL-18 in response to bacterial infection and other insults." (PMID 33479210, 2021). "For example, a short antimicrobial peptide, CM11, has been shown to upregulate key genes such as interleukin 1β (il1β), interleukin 8 (il8), or tumor necrosis factor α (tnfα), boosting the immune system of zebrafish against bacterial infections." (PMID 34769254, 2021). "In our previous study, we demonstrated that IL-1α, IL-1β and IL-1Ra were increased in cirrhotic patients and increased IL-1Ra levels predicted bacterial infection events." (PMID 34648567, 2021). "From this selection three virally upregulated genes (IFI44L, MxA, RSAD2) were further evaluated together with four genes supposedly indicative of bacterial infections (IL-1β, IL-8, FAM89A, S100PBP) on clinical samples." (PMID 34555028, 2021). "The activation of the NF-κB pathway promotes the assembly of the NLRP3 inflammasome and the secretion of IL-1β and IL-18 to intracellular bacterial infection." (PMID 33414782, 2020). "The mRNA expression of both interleukin 1β (IL-1β) and inducible nitric oxide synthase (iNOS) increased in all examined tissues after bacterial infection." (PMID 33239112, 2020). "PM2.5-treatment plus bacterial infection inhibited the production of proinflammatory cytokines including IL-1α, IL-1β, and TNF-α, thereby enhancing bacterial infectivity." (PMID 32753046, 2020). "This prolonged IFN-I and virally induced IL-10 set the scene for secondary bacterial infection, which can add a strong IL1β and TNFα-mediated inflammatory response to magnify lung damage." (PMID 32595654, 2020).
bacterial infection (continued). "We observed that IL-1β increased during bacterial infection but decreased when macrophages were co-stimulated with bacteria and uric acid." (PMID 33322651, 2020). "IL-1β secretion by monocytes is involved in regulating immune and inflammatory responses to bacterial infections and injury, hence its role in innate immunity." (PMID 32045425, 2020). "LAE (i.p.)reduced the level of IL‐1β that increased in mice as a result of bacterial infection (P = 0.0052)." (PMID 31758659, 2020). "Cytokines such as TNF-α, KC, IL-1β, and IL-10, released, among others, by PMNs, orchestrate the innate immune response in bacterial infections." (PMID 33613460, 2020). "Specifically, CT and TT genotypes of rs3804099 are linked with resistance to bacterial infection due to higher TNF-a, IL-1B and IL-6 production in peripheral blood monocytes than CC homozygotes." (PMID 33328979, 2020). "IFN-γ is mainly produced by NK cells and is one of the most important cytokines for the activation of granulocytes, which release proinflammatory cytokines such as IL-6 and IL-1β under bacterial infection." (PMID 33327533, 2020). "This modulation of immunity is also supported by decreased levels of cytokines responsible for controlling bacterial infections, such as IL-1β, IL-6, IL-9, IL-12, TNF-α, IL-17, and IFN-γ, observed in the serum of the WT mice." (PMID 32139610, 2020). "The NOD-like receptors (NLRs) are a specialized group of intracellular innate immune receptors that mediate IL1β production against bacterial infection." (PMID 32851030, 2020). "For example, some evidence supports that mitochondrial fission is important for IL-1β production during bacterial infection." (PMID 33520735, 2020). "The heat map showed that the gene expression levels of 62 DEGs were upregulated and that some of these genes, such as IL-6, IL-1β, CCL2, CXCL2, CXCL8, and CSF3, are closely associated with host defense responses to bacterial infection." (PMID 31737164, 2019). "Neutrophils are unable to undergo pyroptosis and continue to produce IL1β after bacterial infection." (PMID 30728749, 2019). "IFNI, IL1β, and TNFα fine-tune inflammasomes, autophagy, and caspase 8-mediated cell death modes to control many aspects of bacterial infections." (PMID 30728749, 2019). "For the studied Th1 cytokines (IFNγ, TNFα, IL-6, and IL-1β), only IFNγ showed a significant decrease as a consequence of bacterial infection in mechanically ventilated rats." (PMID 31614857, 2019). "Bacterial infection significantly induced the generation of IL-1β, IL-6, and TNF-α in BMMs treated with vehicle." (PMID 30609675, 2019). "Robinson reported that influenza A virus inhibits bacterial-induced IL-1β production and impairs host defense against bacterial infection." (PMID 30691434, 2019). "Autophagocytic responses to bacterial infection limit inflammasome activation and resultant IL-1β secretion." (PMID 29720937, 2018). "These genes mediate the macrophage polarization to M1, a common response of macrophages to bacterial infections, which includes genes encoding TNF, IL-1β, IL-6, and CCL2." (PMID 30064361, 2018). "For example, a Streptococcus ADP-ribosyltransferase, SpyA, triggers an IL-1β-dependent innate immune response pathway that is critical in defense against invasive bacterial infection." (PMID 29887858, 2018). "In the context of intracellular bacterial infections, ILC1s were described to communicate indirectly with DCs via DC-derived IL-12 and IL-1β." (PMID 29623077, 2018). "Our findings are consistent with a previous study in that we showed that IL-1β production is connected with the in vitro efferocytosis and in vivo control of bacterial infection, as well as efferocytosis of pyroptotic cells." (PMID 30518854, 2018). "By contrast, the clo mutant larvae injected with LPS showed few il1b-positive cells, which indicated that tissue injury and bacterial infection induce il1b expression through distinct mechanisms." (PMID 28229859, 2017).
bacterial infection (continued). "Both IL-1β and IL-18 cytokines were expressed intracellularly during bacterial infection, but only the former was released and detected in the extracellular environment." (PMID 28469996, 2017). "Bacterial infection is recognized to trigger an inflammatory response that accompanies the induction of il1b expression." (PMID 28229859, 2017). "Inflammatory cytokine responses, including TNF, IL-1β, IL-6 and IL-12, mediate resistance to bacterial infection." (PMID 28580947, 2017). "The key findings include that both, aprV2 and aprB2 strains of D. nodosus, were able to migrate from the agar plug into tissues after 28 h of exposure, and those tissues responded to bacterial infection with the release of IL1β into the culture supernatant." (PMID 28959685, 2017). "To further investigate the mechanism of IL-1β-induced NF-κB signalling on rendering alveolar epithelial cells hypo-responsive towards subsequent bacterial infection, we developed a kinetic model of ordinary differential equations." (PMID 28931863, 2017). "We chose LPS as a stimulus to mimic bacterial infection and IL-1β as a more selective pro-inflammatory signal." (PMID 28721202, 2017). "Previous studies have shown that melatonin suppresses TNF-α, IL-1β, IL-6, IL-8, and IL-10 during bacterial infections or LPS treatment in vitro and in vivo." (PMID 28542575, 2017). "Pro-inflammatory cytokines such as TNF-α, IL-6 and IL-1β are essential for the recruitment and activation of cells of the immune system in response to bacterial infection." (PMID 28440335, 2017). "Consistent with these in vitro results, oral administration of berberine to mice markedly elevated the levels of soluble IL-1β in the lavage fluids of their peritoneal cavities upon bacterial infection." (PMID 27980220, 2017). "After 6 h of bacterial infection, zebrafish muscles show high induction (∼200-fold) of pro-inflammatory cytokines IL1β and TNFα." (PMID 27101844, 2016). "Interleukin-1β (IL-1β) is a proinflammatory cytokine required for host control of bacterial infections, and its production must be tightly regulated to prevent excessive inflammation." (PMID 27670879, 2016). "IL-1β is important for control of bacterial infections, but when deregulated can lead to excessive inflammation." (PMID 27670879, 2016). "In this respect, the NLRP3 inflammasome plays an important role in IL-1β production in response to bacterial infection." (PMID 28083517, 2016). "In conclusion we have identified a novel negative regulatory role for CARD9 on IL-1β production in macrophages by modulating pro-IL-1β expression and caspase-8 recruitment to the inflammasome in response to bacterial infection." (PMID 27670879, 2016). "Our results showed that the ETT2 ATPase EivC suppressed the expression of the inflammatory cytokines IL-1β and IL-8, and facilitated bacterial infection and virulence." (PMID 27630634, 2016). "Many bacterial diseases are characterized by elevated levels of circulating IL-1β and IL-6 with a concomitant increase in plasma CRP, explaining the good correlation between plasma levels of IL-6 and CRP." (PMID 27977798, 2016). "The results showed that bacterial infection induced IL-1β release into the peritoneal lavage fluids and blood in a time-dependent manner." (PMID 27812336, 2016). "In this study we have identified a new role for CARD9 as a negative regulator of IL-1β production in response to bacterial infection." (PMID 27670879, 2016). "IL-1β is a marker for inflammation because it is produced after a bacterial infection to stimulate the extravasation of leukocytes to the infected sites and to activate the production of antimicrobial effectors." (PMID 27540375, 2016). "Our study reveals that rapid production of anti-Ft LPS IgM by B1a B cells depends on IL-1β and suggests, for the first time, a role for IL-1β in the development of B1a B cells during a bacterial infection." (PMID 25768794, 2015).
bacterial infection (continued). "Further, HO-1 regulates myeloid differentiation as well as immune response to viral or bacterial infection via increased IL-1β release." (PMID 26418896, 2015). "That is, sterile inflammation (i.e. IL-1β) or bacterial infection (i.e. LPS) induced the expression and secretion of pro-inflammatory cytokines from human pregnant adipose tissue and skeletal muscle." (PMID 25541965, 2014). "Of these cytokines, IL-1β is a potent activator of immune responses directed against bacterial infections." (PMID 24628870, 2014). "The APR is the first response to various stressors, such as injury, bacterial infection or systemic inflammation, and is activated by inflammatory mediators, such as tumor necrosis factor alpha (TNFα), IL-1β, IL-6, and GCs." (PMID 25335188, 2014). "Upon exposure to bacterial infection, proinflammatory cytokines like TNFα, IL-1β, and IL-6 are secreted mostly by monocytes or macrophages to defend against bacterial infections." (PMID 23997804, 2013). "IL-1β is secreted in biological fluids and thought to be a primary initiator of the inflammatory cascade during bacterial infection." (PMID 23319831, 2012). "The production and secretion of pro-inflammatory cytokine IL-1β is crucial for stimulating innate immune responses and recruiting the phagocytic cells to defend against tumors and bacterial infection." (PMID 22844468, 2012). "IL-1β was found to be critically important for several other bacterial infections, including S. aureus, B. anthracis, and M. tuberculosis." (PMID 21731762, 2011). "PCT is produced ubiquitously in response to endotoxin or mediators released in response to bacterial infections (that is, interleukin (IL)-1β, tumor necrosis factor (TNF)-α, and IL-6) and strongly correlates with extent and severity of bacterial infections." (PMID 21936959, 2011). "Taken together and including our data, it is clear that IL-1β can play a critical role in the host defense against a bacterial infection." (PMID 21731762, 2011). "It has been reported that under the circumstances of inflammation, or upon bacterial infection, the increased release of inflammatory cytokines such as IL-1β and TNF-α have potent effect on up-regulation of CFTR in epithelial cells." (PMID 21151921, 2010). "Furthermore, the findings revealed that OmTRIM25 is needed to trigger LPS-induced expression of pro-inflammatory cytokines (i.e., TNF-α2 and IL-1β) in RTgill-W1 cells, suggesting a potential immunomodulatory function in the gill during bacterial infection." (PMID 41514764, 2025). "Pro-inflammatory cytokines, such as IL-1β and IL-6, can trigger inflammatory responses, while anti-inflammatory cytokines, like IL-10, support the host immune system in defending against bacterial infections." (PMID 40403037, 2025). "IL-1β may be the dominant cytokine in the inflammatory environment of the CF lung, especially after the onset of bacterial infections." (PMID 40791588, 2025). "In human medicine, it has been demonstrated that bacterial infections cause a significant increase in pro-inflammatory cytokines such as TNF-α and IL-1β, which subsequently induce the overexpression of the CALC-1 gene in various tissues, leading to PCT overproduction." (PMID 41012820, 2025). "For instance, caspase-12 was shown to inhibit mucosal immunity to bacterial infection via suppression of the Nod-Rip2-NF-kB signaling pathway, as well as via inhibition of caspase-1 activation and subsequent IL-1β and IL-18 secretion, although the latter remains controversial." (PMID 41012634, 2025). "Research indicates that the absence of Il1b in mice leads to high susceptibility to group B streptococcus, suggesting a role for Il1b in bacterial infection inhibition." (PMID 39048939, 2024).